Y_RNA (Y RNA )
Gene: Miscellaneous RNA gene on chromosome 2 (61,928,634 to 61,928,704, reverse strand). Ensembl gene ENSG00000278523.
Homologues: Orthologues: chimpanzee Y_RNA (100% identical). Paralogues in human: Y_RNA (83% identical), Y_RNA (82% identical), Y_RNA (80% identical), RNY3 (79% identical), RNY3P1 (79% identical), Y_RNA (79% identical), Y_RNA (77% identical), RNY3P14 (76% identical), RNY3P5 (76% identical), Y_RNA (76% identical), RNY3P12 (75% identical), RNY3P4 (75% identical), and 82 more.